NIBAN3 (niban apoptosis regulator 3)
Synonyms: BCNP1; FAM129C; FLJ39802
Tractability: No criterion of Open Targets' tractability assessment is met for any kind of drug.
Gene: Protein-coding gene on chromosome 19 (17,523,301 to 17,553,839, forward strand). Ensembl gene ENSG00000167483.
Subcellular location (Human Protein Atlas): Cytosol
Gene Ontology:
Molecular function: protein binding
Genetic constraint (gnomAD): Loss-of-function variants: 55 observed, 57.53 expected, observed/expected ratio (o/e) 0.96, 90% interval 0.77 to 1.2. The upper end of that interval is the gene's LOEUF score, 1.2, which puts it in group 5 of 6, group 1 being the genes least tolerant of losing a copy. Missense variants: 643 observed, 616.34 expected, observed/expected ratio (o/e) 1.04, 90% interval 0.98 to 1.11. Synonymous variants: 299 observed, 265.13 expected, observed/expected ratio (o/e) 1.13, 90% interval 1.02 to 1.24.
Homologues: Orthologues: macaque NIBAN3 (95% identical), chimpanzee NIBAN3 (94% identical), pig NIBAN3 (80% identical), dog NIBAN3 (70% identical), rat Niban3 (65% identical), mouse Niban3 (64% identical), guinea pig NIBAN3 (52% identical). Paralogues in human: NIBAN1 (26% identical), NIBAN2 (26% identical).
Diseases named in the same sentence as NIBAN3 in open-access papers:
NIBAN3 is named in the same sentence as 9 diseases in open-access papers, as found by Europe PMC text mining. Sharing a sentence is not in itself a finding about the gene and the disease. The quoted sentences say what the papers report.
COVID-19 (1 paper, 2024). A disease caused by infection with severe acute respiratory syndrome coronavirus 2. "Contrary to CARMIL2 and CCR7, consistent expression of NIBAN3, also known as B-cell novel protein 1 (BCNP1), in SAT under consideration of infection with and without vaccination lacks direct associations with obesity, T2D, or COVID-19." (PMID 38474155, 2024).
Parkinson disease (1 paper, 2024). A progressive degenerative disorder of the central nervous system characterized by loss of dopamine producing neurons in the substantia nigra and the presence of Lewy bodies in the substantia nigra and locus coeruleus. "However, investigations linking NIBAN3 to Parkinson’s disease suggest a potential avenue for further exploration." (PMID 38474155, 2024).
NIBAN3 also shares sentences with these, for which no sentence is quoted: lymphoma (2 papers); tumor (2); cancer (1); colon cancer (1); infection (1); leukaemia (1); Obesity (1).